MIR26A1 (microRNA 26a-1)
Synonyms: hsa-mir-26a-1; MIR26A; MIRN26A1; mir-26a-1
Gene: MicroRNA gene on chromosome 3 (37,969,404 to 37,969,480, forward strand). Ensembl gene ENSG00000199075.
Gene Ontology:
Biological process: miRNA-mediated post-transcriptional gene silencing
Cellular component: RISC complex
Homologues: Orthologues: chimpanzee ptr-mir-26a-1 (100% identical), macaque mml-mir-26a-1 (100% identical), dog MIR26A1 (99% identical), guinea pig MIR26A1 (96% identical), mouse Mir26a-1 (96% identical). Paralogues in human: MIR26B (71% identical), MIR26A2 (69% identical).
Diseases named in the same sentence as MIR26A1 in open-access papers:
MIR26A1 is named in the same sentence as 2 diseases in open-access papers, as found by Europe PMC text mining. Sharing a sentence is not in itself a finding about the gene and the disease. The quoted sentences say what the papers report.
endometriosis (1 paper, 2016). The growth of functional endometrial tissue in anatomic sites outside the uterine body. "Although the rs7372209 T allele in MIR26A1 was also associated with increased endometriosis risk, and the reference C allele was protective against endometriosis development, these differences were not significant after Bonferroni correction." (PMID 27741504, 2016).
MIR26A1 also shares sentences with these, for which no sentence is quoted: Infertility (1 paper).